BUB1B (BUB1 mitotic checkpoint serine/threonine kinase B)
Diseases named in the same sentence as BUB1B in open-access papers (continued):
Sharing a sentence is not in itself a finding about the gene and the disease.
rhabdomyosarcoma (4 papers, 2016 to 2023). A rare aggressive malignant mesenchymal neoplasm arising from skeletal muscle. "Interestingly, patients with mosaic variegated aneuploidy syndrome, a rare disorder with has biallelic or heterozygous mutations of the Bub1B gene, have constitutional aneuploidy and a predisposition to early childhood cancer including rhabdomyosarcoma, leukemia and Wilm's tumor." (PMID 27074562, 2016). "Bub1b is a spindle assembly checkpoint protein that is of critical importance for growth and survival of both alveolar and embryonic rhabdomyosarcoma cells." (PMID 27074562, 2016). "A FoxM1/Bub1b signaling pathway is an identified required component for survival and growth of rhabdomyosarcoma." (PMID 27074562, 2016). "Finally, FOXM1 is important in rhabdomyosarcoma wherein it directly binds to the Bub1b promoter, which has a FOXM1 consensus-binding site." (PMID 27074562, 2016). "Tumor predisposition has been observed in patients with biallelic LoF of BUB1B, TRIP13, and MAD1L1, with resulting elevated risks for rhabdomyosarcoma, Wilms tumor, and a variety of malignancies, respectively." (PMID 37796616, 2023).
acute myeloid leukemia (3 papers, 2009 to 2025). Acute myeloid leukemia (AML) is a group of neoplasms arising from precursor cells committed to the myeloid cell-line differentiation. "The upregulation of BUB1B, CCNA2, and CCNB2 in pathway studies is associated with the development of Human T-cell leukemia virus 1 infection and Acute myeloid leukemia." (PMID 40100920, 2025).
pancreatic adenocarcinoma (3 papers, 2018 to 2024). "It is reported that deleterious variant in BUB1B gene is more frequent in patients with familial pancreatic adenocarcinoma." (PMID 29596435, 2018).
psoriasis (3 papers, 2022 to 2023). An autoimmune condition characterized by red, well-delineated plaques with silvery scales that are usually on the extensor surfaces and scalp. "Based on this, we sought to investigate the role of BUB1B in pan-cancer and provide potential molecular mechanisms for psoriasis and the concomitant high risk of cancer." (PMID 37055476, 2023). "Since our prior research indicated that BUB1B contributes to the development of psoriasis, we designed and carried out this investigation using bioinformatics analysis." (PMID 37055476, 2023). "It was found that BUB1B/hsa-miR-130a-3p axis, closely related to the development of psoriasis, also plays a remarkable role in multiple cancer development." (PMID 36185088, 2022). "The most striking result to emerge from the data is that BUB1B/hsa-miR-130a-3p axis, closely related to the development of psoriasis, also plays a remarkable role in multiple cancer development." (PMID 36185088, 2022). "Through bioinformatics research, we discovered that the BUB1B/hsa-miR-130a-3p axis is closely related to the development of psoriasis as well as several cancer types." (PMID 36185088, 2022). "According to our prior research, BUB1B might be a gene that bridges the gap between psoriasis and cancer development." (PMID 37055476, 2023). "It is the first time that BUB1B and DLGAP5 have been linked to the onset of psoriasis, though exact mechanisms are yet unknown." (PMID 36185088, 2022). "All these results revealed that BUB1B as well as DLGAP5 may bridge the gap between psoriasis and cancers." (PMID 36185088, 2022). "After the identification and validation of DEGs, BUB1B and DLGAP5 were finally found as core genes in the development of psoriasis." (PMID 36185088, 2022). "Additionally, the expression of BUB1B and DLGAP5 in the blood samples of psoriasis patients was also higher than that of normal controls." (PMID 36185088, 2022).
adenoma (2 papers, 2018 to 2020). A neoplasm arising from the epithelium. "Comparing of corresponding adenomas, the expressions of BUB1, BUB1B, PLK4, and DNA2 in carcinomas were higher." (PMID 33134313, 2020). "Adult carcinomas express less TCF21 than adenomas, in addition, the KEGG pathway analysis has shown that BUB1B, among others genes, is negatively correlated with TCF21 expression." (PMID 29520253, 2018).
cholangiocarcinoma (2 papers, 2023 to 2024). A carcinoma that arises from the intrahepatic biliary tree (intrahepatic cholangiocarcinoma) or from the junction, or adjacent to the junction, of the right and left hepatic ducts (hilar cholangiocarcinoma). "BUB1 and BUB1B may accelerate the process of cholangiocarcinoma by promoting the mitosis of cholangiocytes." (PMID 36979826, 2023).
Cirrhosis (2 papers, 2018 to 2022). A chronic disorder of the liver in which liver tissue becomes scarred and is partially replaced by regenerative nodules and fibrotic tissue resulting in loss of liver function. "It is concluded that BUB1B, NUSAP1, TTK, HMMR, CCNA2, and KIF2C can be considered as potential novel molecular indicators for the onset and development of HCC, since they are linked to the transition from cirrhosis to HCC." (PMID 36199789, 2022).
colorectal adenocarcinoma (2 papers, 2021 to 2025). The most common type of colorectal carcinoma. "On the other hand, there are contradictory reports showing that BUB1B was dramatically reduced in colorectal adenocarcinomas and polyploid cells." (PMID 33431813, 2021). "However, BUB1B showed opposite results in polyploid cells and colorectal adenocarcinomas." (PMID 41163302, 2025).
dilated cardiomyopathy (2 papers, 2025). Cardiomyopathy which is characterized by dilation and contractile dysfunction of the left and right ventricles. "For dilated cardiomyopathy (DCM), a progressive degenerative disease of the myocardium that is intractable with no curative treatment except heart transplantation, BUB1B was predicted as an inhibitory target." (PMID 39880378, 2025).
endometriosis (2 papers, 2020 to 2025). The growth of functional endometrial tissue in anatomic sites outside the uterine body. "Our study has identified eight potential mitosis hub genes (KIF4A, BUB1B, NEK2, FBXO5, KIF11, CENPE, CCNA2, and NCAPG) that exhibit excellent diagnostic properties for endometriosis." (PMID 40772274, 2025). "Then, we identified 11 potential mitosis-related downregulated hub genes, among which eight genes (KIF4A, BUB1B, NEK2, FBXO5, KIF11, CENPE, CCNA2, and NCAPG) showed good diagnostic properties of endometriosis and two genes (CCNA2, CENPE) were closely related to infertile endometriosis." (PMID 40772274, 2025). "We used the GSE25628 dataset to detect the expression of selected target genes, and the results showed that the differential expression of eight MRHGs (KIF4A, BUB1B, NEK2, FBXO5, KIF11, CENPE, CCNA2, and NCAPG) between control and endometriosis patients was consistent with predictions." (PMID 40772274, 2025).
endothelial dysfunction (2 papers, 2023 to 2024). In vascular diseases, endothelial dysfunction is a systemic pathological state of the endothelium (the inner lining of blood vessels) and can be broadly defined as an imbalance between vasodilating and vasoconstricting substances produced by (or acting on) the endothelium. "Overall, these findings suggest a role of Bub1b, and thereby genomic instability, in vascular aging in mice, leading to endothelial dysfunction, ECM remodeling, and senescence." (PMID 37895059, 2023).
fibrosis (2 papers, 2023 to 2024). the formation of excess fibrous connective tissue in an organ or tissue in a reparative or reactive process. "To date, there have been limited reports on the relationships between CCNB2, NCAPG, KIF20A, KIF11, and BUB1B with SSc or fibrosis." (PMID 38343538, 2024).
hereditary cancer syndrome (2 papers, 2024). "Available data from 1,416 patients screened with the TruSight Cancer Panel at the Department of Laboratory Genetics of IPO Porto for different hereditary cancer syndromes showed nine carriers of BUB1B variants." (PMID 39014450, 2024). "Additionally, 0.6% of the cancer patients fulfilling the criteria for genetic testing for other hereditary cancer syndromes were also carriers of rare BUB1B germline variants, following the pan-cancer profile observed for known moderate- to high-penetrance risk genes." (PMID 39014450, 2024). "To unveil BUB1B as a new PrCa predisposing gene, we performed targeted next-generation sequencing in germline DNA from 462 early-onset/familial PrCa patients and 1,416 cancer patients fulfilling criteria for genetic testing for other hereditary cancer syndromes." (PMID 39014450, 2024).
liver fibrosis (2 papers, 2020 to 2023). "Concluded, the core genes of AFB1-liver fibrosis-HCC were BUB1B and RRM2 genes." (PMID 36829489, 2023). "the top ten core genes were identified using four different algorithm methods and the combined the combined core genes showed that the BUB1B and RRM2 genes were core genes of AFB1-liver fibrosis-HCC." (PMID 36829489, 2023). "The result showed that the BUB1B and RRM2 genes were hub genes in AFB1-liver fibrosis-HCC progression." (PMID 36829489, 2023).
metastatic disease (2 papers, 2015 to 2026). "Consistent with our data from animal model studies, these results indicate that high level expression of BUB1B may promote more advanced and metastatic disease." (PMID 26000094, 2015).
nasopharyngeal carcinoma (2 papers, 2019 to 2022). A carcinoma arising from the nasopharyngeal epithelium. "In addition, another study showed that the expression of BUB1B and CENPF were up-regulated in nasopharyngeal carcinoma and their high expression was associated with poor OS." (PMID 30393234, 2019). "Nevertheless, the influence of BUB1B expression on the occurrence and progression of nasopharyngeal carcinoma (NPC) is still unclear." (PMID 36577966, 2022). "First, due to the lack of data, only one dataset was used to evaluate the effect of BUB1B on the prognosis of nasopharyngeal carcinoma patients, which may not be comprehensive." (PMID 36577966, 2022).
oral cancer (2 papers, 2021 to 2025).
papillary renal cell carcinoma (2 papers, 2022 to 2025). A rare subtype of renal cell carcinoma, arising from the renal tubular epithelium and showing a papillary growth pattern, which typically manifests with hematuria, flank pain, palpable abdominal mass or nonspecific symptoms, such as fatigue, weight loss or fever. "BUB1B expression is positively related to the infiltration of CD4 + T cells and macrophages in papillary renal cell carcinoma." (PMID 41163302, 2025).
renal cell carcinoma (2 papers, 2022 to 2025). "In renal cell carcinoma, BUB1B expression is positively correlated with inflamed CD8+ T cells, nivolumab sensitivity, exhausted T‐cell signature, and IFN‐γ signature." (PMID 41163302, 2025). "A recent study found that BUB1B overexpression is an independent prognostic marker in renal cell carcinoma, which is similar to our findings." (PMID 35037540, 2022).
salivary duct carcinoma (2 papers, 2020 to 2022). An aggressive, high grade adenocarcinoma that arises from the salivary glands. "It has also been demonstrated that MAD2L1 binds with CDC20 and BUB1B and contributes to the abnormal growth of salivary duct carcinoma, despite its participation in signaling transductions." (PMID 36497125, 2022). "Despite the barely known signaling pathways it participated in, MAD2L1 is shown to interact with CDC20 and BUB1B, and correlate with aberrant development of salivary duct carcinoma." (PMID 32795325, 2020).
alcohol- (1 paper, 2021). "In the future research, we need explore the exact molecular mechanisms of these immune cells in alcohol-related HCC and learned whether CENPF and BUB1B can affect the development of alcohol-related HCC through the regulation of immune cells." (PMID 34646769, 2021).
carcinoma in situ (1 paper, 2010). "There was a significantly lower expression of the spindle checkpoint proteins in carcinoma in situ compared to normal testis (P=0.008 and P=0.043 for BUB1B and MAD2, respectively), while the level of AURKA was increased, however, not significantly (P=0.18)." (PMID 20411023, 2010). "In carcinoma in situ of TGCTs the spindle checkpoint proteins MAD2 and BUB1B are significantly less expressed compared to normal testis, while the expression of AURKA is increased." (PMID 20411023, 2010).
chronic myelogenous leukemia (1 paper, 2022). "Abnormal expression of Forkhead box protein M1 (FOXM1) and serine/threonine kinase Budding uninhibited by benzimidazoles 1 (BUB1B) contributes to the development and progression of several cancers, including chronic myelogenous leukemia (CML)." (PMID 35847923, 2022).
ciliopathy (1 paper, 2015). A genetic disorder of the cellular cilia or the cilia anchoring structures, the basal bodies, or of ciliary function. "The four ciliopathy genes (BUBR1 [BUB1B], IFT80, KIF7 and TMEM216) we identified as modifiers of progenitor proliferation encode proteins localized to distinct ciliary compartments." (PMID 26206566, 2015). "We also observed that knockdown of ciliopathy genes ALMS1, BUBR1 [BUB1B], IFT80, NPHP1, NPHP8 [RPGRIP1L], TCTN2, TMEM216 and TUB retarded neuronal migration." (PMID 26206566, 2015).
diabetes (1 paper, 2022). "Nonetheless, none of the expression of ASPM, CDC20, DLGAP5, BUB1B, CDCA8, and NCAPG was related to BMI and diabetes." (PMID 36186000, 2022).
embryonal tumors (1 paper, 2021). "It has been reported that individuals having biallelic TRIP13 or BUB1B mutations are prone to having embryonal tumors, and their cells display severe spindle assembly checkpoint (SAC) impairment." (PMID 33726794, 2021).
familial cancers (1 paper, 2021).
female infertility (1 paper, 2021). Diminished or absent ability of a female to achieve conception. "In these mice, transcription of the ‘H’ allele leads to a precursor mRNA which is occasionally spliced abnormally, causing the development of mutant mature Bub1b mRNA that is not translated; this reduces the cellular BUB1B protein levels, leading to male and female infertility." (PMID 33665191, 2021).
fibrosarcoma (1 paper, 2021). A malignant mesenchymal fibroblastic neoplasm affecting the soft tissue and bone. "BUB1B was upregulated in fibrosarcoma, pleomorphic liposarcoma, malignant fibrous histiocytoma, round cell liposarcoma, synovial sarcoma, and leiomyosarcoma." (PMID 33872216, 2021).
head and neck squamous cell carcinoma (1 paper, 2024). A squamous cell carcinoma that arises from any of the following anatomic sites: lip and oral cavity, nasal cavity, paranasal sinuses, pharynx, larynx, and salivary glands. "BUB1B expression level was negatively correlated with the CAF infiltration of BRCA, HNSC-HPV + (HPV-associated head and neck squamous cell carcinoma), TGCT, and THYM and endothelium infiltration of BRCA, KIRC, LUAD, STAD, and THYM." (PMID 39048649, 2024).
Hypertension (1 paper, 2025). The presence of chronic increased pressure in the systemic arterial system. "BUB1B and CDK1, key regulators of mitosis and cell cycle progression, likely reflect proliferative vascular responses and endothelial turnover in hypertension." (PMID 40909129, 2025).
hypoxic-ischemic encephalopathy (1 paper, 2024). "Given the rarity not only of SUPC but above all of the BUB1B mutation, the aim of this case report is to inform the scientific community of the possibility of a correlation between the BUB1B mutation and the onset of a SUPC with consequences of hypoxic-ischemic encephalopathy." (PMID 38664248, 2024).
idiopathic inflammatory myopathies (1 paper, 2024). "Bub1b encodes a protein associated with mitotic checkpoint control, and Ccl3 is a critical chemokine for idiopathic inflammatory myopathies, with high expression in injured skeletal muscle and responsible for recruiting Treg cells to these sites." (PMID 38339055, 2024).
immune deficiency (1 paper, 2025). "BUB1B induced polyploid cell apoptosis and inhibited the growth of tumors in nude mice with immune deficiency." (PMID 41163302, 2025).
lactic acidosis (1 paper, 2013). Metabolic acidosis characterized by the accumulation of lactate in the body. "Since hyperactivated mitotic checkpoint is another major mechanism that leads to human tumor CIN, we tested if glucose deprivation with lactic acidosis could disturb the expression of the mitotic checkpoint genes such as mad2, bub1, bub3, and bub1b." (PMID 23675453, 2013).
leiomyosarcoma (1 paper, 2021). An uncommon, aggressive malignant smooth muscle neoplasm, usually occurring in post-menopausal women. "BUB1B was upregulated in dedifferentiated liposarcoma, myxofibrosarcoma, pleomorphic liposarcoma, leiomyosarcoma, and myxoid/round cell liposarcoma with fold changes of 3.628 (P = 2.20E-17), 7.544 (P = 1.11E-17), 5.121 (P = 8.66E-13), 4.838 (P = 1.46E-10), and 2.842 (P = 1.88E-10), respectively." (PMID 33872216, 2021).
lentivirus infection (1 paper, 2022). Virus diseases caused by the Lentivirus genus. "To explore the specific function of BUB1B in THCA, we used lentivirus infection to knock down the BUB1B, and then performed flow cytometry, colony formation, transwell, and wound-healing assays." (PMID 35517426, 2022).
leukemia (1 paper, 2022). A malignant (clonal) hematologic disorder, involving hematopoietic stem cells and characterized by the presence of primitive or atypical myeloid or lymphoid cells in the bone marrow and the blood. "However, the molecular mechanism of the FOXM1/BUB1B regulatory network and the role of Neosetophomone-B (NSP-B) in leukemia remains unclear." (PMID 35847923, 2022).
lymphoma (1 paper, 2013). A malignant (clonal) proliferation of B- lymphocytes or T- lymphocytes which involves the lymph nodes, bone marrow and/or extranodal sites. "Median expression levels were invariably higher for AURKB, BCAT1, BIRC5, BUB1B, PBK and RACGAP1 and lower for FOSB, MAP3K1 and RIN3 by qPCR in lymphoma versus normal B cell samples in both species." (PMID 24130802, 2013).
mosaic variegated aneuploidy syndrome 1 (1 paper, 2024). "Mutations in the BUB1B gene are linked to mosaic variegated aneuploidy syndrome 1 (MVA1), a rare autosomal recessive disorder characterized by diffuse mosaic aneuploidies involving several chromosomes and tissues." (PMID 38664248, 2024).
multiple sclerosis (1 paper, 2016). A progressive autoimmune disorder affecting the central nervous system resulting in demyelination. "Interestingly, a recent microarray analysis shows a reduced level of BUB1B in demyelinating lesions of patients with multiple sclerosis." (PMID 27922816, 2016).
ovarian insufficiency (1 paper, 2022). "BUB1B variants cause ovarian insufficiency and early menopause." (PMID 35719392, 2022).
ovarian serous carcinoma (1 paper, 2022). "BUB1B was also involved in the molecular regulation of EMT and associated with poor early survival of ovarian serous carcinoma at stages I+II 33, indicating BUB1B as a key biomarker for early clinical diagnosis and prognosis evaluation of patients." (PMID 35517426, 2022).
pleural mesothelioma (1 paper, 2024). A neoplasm that arises from the mesothelial cells of the pleura. "All PM (pleural mesothelioma) (frequency > 4%) had BUB1B gene deep deletion." (PMID 39048649, 2024).